IDH2 (isocitrate dehydrogenase (NADP(+)) 2)
Diseases named in the same sentence as IDH2 in open-access papers (continued):
Sharing a sentence is not in itself a finding about the gene and the disease.
lymphoma (8 papers, 2018 to 2025). A malignant (clonal) proliferation of B- lymphocytes or T- lymphocytes which involves the lymph nodes, bone marrow and/or extranodal sites. "In difficult cases, the presence of RHOA and/or IDH2 mutations supports the diagnosis of TFH lymphoma." (PMID 37747559, 2024). "IDH2 gene mutation status is available from the lymphomas of five of the included MPN-AITL patients." (PMID 34771688, 2021). "In mouse models, TET2 deficiency and RHOA mutations promote TFH polarization via ICOS/PI3K-MAPK signaling, leading to lymphoma development, while IDH2 further augments this process through TET inhibition." (PMID 41295262, 2025). "Recurrent somatic mutations in multiple epigenetic regulators, including loss-of-function mutations in TET2, inactivating mutations in DNMT3A and neomorphic mutations in IDH2, have been strongly associated with nodal TFH lymphomas." (PMID 37841428, 2023). "In particular, lymphoma samples with concurrent myeloid disease showed high variations in IDH2 expression compared with the R-AITL samples, which was consistent with the high differences in expression that were also found in the proteomic analysis." (PMID 34771688, 2021). "The mutational landscape of TFH lymphoma includes genes involved in epigenetic pathways such as TET2 (up to 90%), IDH2 (20–45%), and DNMT3A (20–30%), mutations in the small GTPase RHOA (50–70%) and mutations in the TR signaling pathway including PLCG1, CD28, FYN, and VAV1." (PMID 37747559, 2024). "Furthermore, frequent mutations at isocitrate dehydrogenase 2 arginine 172 (IDH2 R172) have also been identified in AITL and other TFH-derived lymphomas." (PMID 37841428, 2023). "Unfortunately, an evaluation of the IDH2 gene mutation status of the entire MPN-lymphoma cohort was not possible because of unavailability (or poor quality) of the tissue specimens that were acquired for sequencing." (PMID 34771688, 2021). "Thus, nodal TFH-derived lymphomas with IDH2 R172 mutations are predicted to have repressed TET activity and accordingly IDH2-mutated AITL exhibits genome-wide DNA hypermethylation compared to IDH2 wild-type AITL." (PMID 37841428, 2023). "As reported in other studies, the representative genetic alterations to induce a robust T follicular helper phenotype (RHOA, IDH2, and DNMT3A) of AITL also appeared in other TFH lymphomas." (PMID 33990228, 2021). "Mutations related to the RAS family (RHOA) and those related to epigenetic regulators (IDH2, DNMT3A, and TET2) were shown mainly in AITL and other TFH lymphomas." (PMID 33990228, 2021). "In nTFHL-AI particularly, RHOA and IDH2 show promise as MRD markers because they are not present in pre-lymphoma clones." (PMID 41295262, 2025). "Notably, mutations related to the RAS family (RHOA) and those related to epigenetic regulators (IDH2, DNMT3A, and TET2) were found mainly in AITL and other TFH lymphomas." (PMID 33990228, 2021). "Similarly, the mutational profile of FTCL seems to be similar to other nodal TFH lymphomas with mutations in TET2, DNMT3A, and RHOAG17V, but not in IDH2 which are usually restricted to AITL." (PMID 36793612, 2023).
malignant glioma (8 papers, 2012 to 2024). A grade III or grade IV glioma arising from the central nervous system. "Mutations in NADP(+)-dependent isocitrate dehydrogenases coded by the IDH1 and IDH2 are seen in the majority of malignant gliomas." (PMID 38686271, 2024). "Furthermore, we found no somatic mutation in Idh1, Idh2, or H3f3a (mutated in pediatric GBMs) in malignant gliomas and GBMs from all three models, which were more similar to the human IDH-WT GBMs without exhibiting G-CIMP 22,24." (PMID 32699356, 2020).
Obesity (8 papers, 2018 to 2025). Accumulation of substantial excess body fat. "In addition, given the close relationships among obesity, abnormal lipid metabolism, and inflammation, we investigated the effect of IDH2 deficiency on lipid accumulation and inflammation in the liver." (PMID 36130994, 2022). "Additionally, it was reported that IDH2 deficient mice are resistant to obesity and hepatic steatosis via the suppression of lipogenesis and the elevation of thermogenesis in the liver and adipose tissues." (PMID 31546946, 2019). "To assess the role of miR204 in the development of fatty liver and obesity in IDH2 KO mice, we compared subcutaneous fat accumulation and blood parameters between WT and KO mice fed an ND or HFD for 12 weeks." (PMID 36130994, 2022). "IDH2 deletion increased obesity resistance and metabolic stress through brown adipose tissue whitening." (PMID 36130994, 2022). "RBP4 is a useful biomarker for diagnosing obesity and the prognosis of related diseases, while IDH2 affects brown adipose tissue thermogenesis." (PMID 36467654, 2022). "IDH2 has been suggested as a potential therapeutic target in the treatment of type 2 diabetes and obesity due to its major role in modulating both insulin sensitivity and fuel metabolism in mice." (PMID 31234367, 2019). "Targeting IDH2 may represent a potential therapeutic strategy to mitigate metabolic dysfunction in offspring exposed to maternal prepregnancy obesity." (PMID 40256914, 2025). "We previously reported that IDH2 deficiency influenced high-fat-diet-induced obesity and hepatic steatosis in aged male mice; yet it is not known how IDH2 deficiency is interlinked with NAFLD." (PMID 29861476, 2018). "Moreover, we discovered significant enrichment of H3K9me3 at the IDH2 promoter region in the muscle tissue of offspring exposed to prepregnancy obesity, which could be originated from the increased H3K9me3 levels in the oocytes from HFD‐fed dams." (PMID 40256914, 2025). "Given the strong link between mitochondrial biogenesis and muscle fibre composition, we hypothesised that IDH2 modulates muscle fibre transition by maintaining redox homeostasis and enhancing PGC‐1α‐mediated mitochondrial biogenesis in offspring exposed to maternal prepregnancy obesity." (PMID 40256914, 2025).
T-cell lymphomas (8 papers, 2016 to 2025). "Another recent study of T-cell lymphoma has also reported a significantly increased hypermethylation in ISYNA1 for IDH2 mutant samples." (PMID 30791611, 2019). "The T-cell lymphoma panel showed no mutations in RHOA, TET2, DNMT3A, IDH2, and other genes typically altered in TFH-derived and other T-cell lymphomas in both lymph node and BM specimens, further supporting the diagnosis of NMZL." (PMID 41515931, 2025).
anaplastic astrocytoma (7 papers, 2014 to 2024). "Our chondrosarcoma cell line panel contained one homozygous mutant IDH2 cell line (L2975) that, contradictory to what has been shown in the anaplastic astrocytoma WHO grade III cell line IMA, revealed elevated levels of D-2-HG comparable to heterozygous mutant IDH1/2 cell lines." (PMID 25895133, 2015). "A series of 193 patients with astrocytic neoplasms (111 diffuse and 82 anaplastic astrocytomas), grouped according to prelabeled anatomical structures and the risk of surgery, were retrospectively reviewed for IDH1 and IDH2 mutations to compare the tumor location and MRI features." (PMID 24932255, 2014).
gastric cancer (7 papers, 2016 to 2023). A primary or metastatic malignant neoplasm involving the stomach. "IDH2 is associated with the occurrence and prognosis of gastric cancer." (PMID 33981605, 2021). "Furthermore, low IDH2 expression levels have been closely associated with the poor survival curve in patients with gastric cancer." (PMID 29661250, 2018). "It was found that the expression level of IDH2 in gastric cancer was significantly decreased, and the low expression level of IDH2 was significantly correlated with the survival rate of patients with gastric cancer." (PMID 33981605, 2021). "The overexpression of IDH2 can increase the level of 5hMC in gastric cancer cells, while the low expression of IDH2 may lead to the depletion of 5hMC in gastric cancer cells." (PMID 33981605, 2021). "The down-regulation of IDH2 inhibited the growth and movement of gastric cancer cells." (PMID 33981605, 2021). "However, only IDH2 expression levels were significantly lower in gastric cancer tissues than in adjacent normal tissues." (PMID 29661250, 2018). "We also revealed that IDH1 and IDH2 modulate 5hmC levels in human gastric cancer." (PMID 29661250, 2018). "Indeed, our results show that isocitrate dehydrogenase (IDH2), an enzyme in the citric acid cycle, is down regulated in advanced gastric cancer." (PMID 27941907, 2016). "IDH2 levels were decreased in kidney cancer, hepatocellular carcinoma (HCC), and gastric cancer (GC), compared to normal tissues." (PMID 31010244, 2019).
Maffucci syndrome (7 papers, 2014 to 2025). Maffucci syndrome is a very rare genetic bone and skin disorder characterized by multiple enchondromas, leading to bone deformities, combined with multiple dark, irregularly shaped hemangiomas or less commonly lymphangiomas. "It has been reported that somatic mosaic isocitrate dehydrogenase type 1 (IDH1) or isocitrate dehydrogenase type 2 (IDH2) mutations are associated with Maffucci’s syndrome." (PMID 34790172, 2021). "The majority of Maffucci syndrome cases are attributed to somatic mutations in the IDH1 gene, with a smaller proportion linked to IDH2 mutations." (PMID 40420921, 2025). "Heterozygous somatic mutations in the isocitrate dehydrogenase 1 and 2 (IDH1/IDH2) genes are associated with a number of different tumor types (e.g. IHCC) and also with Maffucci syndrome." (PMID 26920730, 2016).
myeloproliferative neoplasm (7 papers, 2012 to 2021). A clonal hematopoietic stem cell disorder, characterized by proliferation in the bone marrow of one or more of the myeloid (i.e., granulocytic, erythroid, megakaryocytic, and mast cell) lineages. "IDH1 and IDH2 mutations were also identified in chronic myeloid neoplasms, including MDS and myeloproliferative neoplasms (MPNs)." (PMID 26668680, 2016).
oligodendroglial tumor (7 papers, 2013 to 2020). Oligodendrogliomas are cerebral tumors that are differentiated from other gliomas on the basis of their unique genetic characteristics and better response to chemotherapy. "All mutations affected codon R132 of the IDH1 gene, with the exception of one oligodendroglial tumor with mutation at codon R172 of the IDH2 gene." (PMID 24083241, 2013). "EMP3 promoter hypermethylation is significantly associated with IDH1/IDH2 mutations in both astrocytic and oligodendroglial tumors." (PMID 24083241, 2013). "Mutation of the isocitrate dehydrogenase enzyme isoform 1 (IDH1 R132) and 2 (IDH2 R172) is associated with a large proportion of diffuse astrocytic and oligodendroglial tumors." (PMID 24179531, 2013). "Furthermore despite the high frequency of IDH1 p.R132H mutations detected in oligodendroglial tumors, we found that 13.6% (6/44) of O2s had IDH2, IDH1 p.R132G or IDH1 p.R132S mutations." (PMID 25257301, 2014). "Interestingly IDH2 mutations were restricted to oligodendroglial tumors with a similar distribution between O2 and O3." (PMID 25257301, 2014). "We found that the distribution of IDH1R132H, IDH1nonR132H, and IDH2 mutations differed between astrocytic, mixed, and oligodendroglial tumors, with an overrepresentation of IDH2 mutations in oligodendroglial phenotype and an overrepresentation of IDH1nonR132H in astrocytic tumors." (PMID 24877111, 2014). "Patient stratification for the histological type revealed that EMP3 promoter hypermethylation was significantly associated with IDH1/IDH2 mutations in astrocytic tumors (P = 0.0088), GBMs included (P = 0.0012), in oligodendroglial tumors (P = 0.0006), and in oligoastrocytomas (P = 0.0095)." (PMID 24083241, 2013). "In oligodendroglial tumors, it was strongly associated with both IDH1/IDH2 mutations and total 1p/19q codeletion and inversely with EGFR gene amplification." (PMID 24083241, 2013). "In oligodendroglial tumors, it is strongly associated with both IDH1/IDH2 mutations and total 1p/19q codeletion and inversely with EGFR gene amplification." (PMID 24083241, 2013). "No IDH2 mutations were identified in our patients with primary–progressive paired oligodendroglial tumors." (PMID 23826216, 2013).
ovarian carcinoma (7 papers, 2021 to 2023). A malignant neoplasm originating from the surface ovarian epithelium. "However, such mutations in IDH2 seldom occur in ovarian cancer, implying that overexpression of IDH2 promotes OC progression by facilitating TCA cycle activity to produce enough energy and not by producing 2-HG." (PMID 37210576, 2023). "Moreover, EZH2 and IDH2 are overexpressed in ovarian cancer stem cells, which favor OXPHOS over glycolysis for energy production." (PMID 37210576, 2023).
astrocytic tumor (6 papers, 2013 to 2024). A glial tumor of the brain or spinal cord showing astrocytic differentiation. "IDH2 mutation is extremely rare in astrocytic tumors and is more often associated with an oligodendroglial phenotype." (PMID 39192927, 2024). "We investigated ATRX mRNA expression and its association with IDH1 and IDH2 mutations in 169 adult astrocytic tumors using whole transcriptome sequencing." (PMID 24810474, 2014). "In the GLASS and MSK diffuse glioma datasets, we found only one IDH2-mutant astrocytic tumor in the entire cohort." (PMID 38012788, 2023).
hepatocellular carcinoma (6 papers, 2014 to 2026). A malignant tumor that arises from hepatocytes. "In addition, IDH2 expression was reduced in some cancers, such as renal, gastric, and hepatocellular carcinomas, and IDH2 inhibited metastatic invasion of gastric and hepatocellular carcinoma cells via matrix metalloproteinases." (PMID 36497259, 2022). "Interestingly, IDH2 expression in hepatoma cells exhibits an unusual increase after hypoxia, suggesting that IDH2 collaborates with the antioxidant system to regulate NADPH production and redox homeostasis in hypoxic cancer cells." (PMID 26956544, 2016). "5-hmC and IDH2 expression in hepatocellular carcinoma (HCC) has yet to be determined." (PMID 24716838, 2014).
low grade glioma (6 papers, 2013 to 2024). A grade I or grade II glioma arising from the central nervous system. "Mutations in IDH1and IDH2 are associated with higher overall survival rates and aremore commonly found in low-grade gliomas (LGG)." (PMID 39186481, 2024). "• Mutations in IDH1 and IDH2 havebeen evidenced inover 80% of low-grade gliomas (LGGs) and secondary GBM." (PMID 35786935, 2022). "Somatic mutations of the isocitrate dehydrogenase 1 and 2 genes (IDH1 and IDH2) are frequent and early events in the pathogenesis of low-grade gliomas as well as in a small subset of GBMs." (PMID 30567605, 2018).
sinonasal carcinomas (6 papers, 2021 to 2024). "One distinguishing difference between this group of lethal carcinomas and SMARCA4-deficient sinonasal carcinomas is IDH2 mutation." (PMID 39590317, 2024). "DNA methylation profiling of olfactory neuroblastomas and a cohort of sinonasal carcinomas showed that IDH2 mutated and SMARCB1 deficient carcinomas likely represent epigenetically distinct classes." (PMID 36443295, 2022). "On the other hand, small-cell SNECs and SMARCB1-deficient sinonasal carcinomas seem to be molecularly distinct from IDH2-mutated carcinomas, as supported by the distribution of ARID1A mutations, which were common in small-cell SNEC but not among IDH2-mutant cancers." (PMID 35059992, 2022). "The positivity of IDH2 11C8B1 on IHC in sinonasal carcinomas would be highly predictive of the presence of IDH2 R172S/T mutations in around 70% of cases." (PMID 36431263, 2022). "Poorly differentiated sinonasal carcinomas (PDSNCs) are rare neoplasms that include a wide spectrum of malignancies characterized by alteration in different epigenetic mechanisms (SWI/SNF complex, IDH2, NUT)." (PMID 34638515, 2021).
sinonasal undifferentiated carcinoma (6 papers, 2021 to 2025). A rare, highly aggressive carcinoma that arises from the sinonasal tract. "Mutations affecting codon 172 of the isocitrate dehydrogenase 2 (IDH2) gene define a subgroup of sinonasal undifferentiated carcinomas (SNUCs) with a relatively favorable prognosis and a globally hypermethylated phenotype." (PMID 38928223, 2024). "Therefore, it is possible that IDH2 mutant tumors could be sinonasal undifferentiated carcinomas (SNUC), which are highly positive for cytokeratins and more commonly harbor IDH2 mutations." (PMID 37377616, 2023).
thyroid cancer (6 papers, 2016 to 2025). "First, FN1, IDH2, and VDAC1 were more highly expressed in thyroid cancer tissues than in normal tissues; however, FABP4 and TG were less highly expressed in thyroid cancer tissues." (PMID 36418670, 2023).
acute promyelocytic leukemia (5 papers, 2012 to 2025). An aggressive form of acute myeloid leukemia (AML), characterized by arrest of leukocyte differentiation at the promyelocyte stage, due to a specific chromosomal translocation t(15;17) in myeloid cells. "So far, this concept has been successful by using all-trans retinoic acid (ATRA) and/or arsenic trioxide in the therapy of acute promyelocytic leukemia (APL), as well as by introducing midostaurin and enasidenib in the therapy of AML with FLT3 and IDH2 mutations, respectively." (PMID 30728457, 2019). "Interestingly, we observed that both IDH1 and IDH2 mutations were predominantly found in AML with maturation (AML-M2; n = 24/44) and acute promyelocytic leukemia (APL) (AML-M3; n = 11/44) which were different from AML-M1 as reported by others." (PMID 22397365, 2012).
anaplastic gliomas (5 papers, 2013 to 2023). "Similarly among the recurrent tumors, IDH1/IDH2 mutation was detected in 77% (10/13) of LGGs, 61% (11/18) of anaplastic gliomas and 50% (11/22) of GBM, with 79% (11/14) of secondary GBM harbored the mutation." (PMID 23840696, 2013). "Mutations in the NADP+ dependent isocitrate dehydrogenase genes IDH1 and IDH2 are involved in the pathogenesis of a subgroup of diffuse and anaplastic gliomas." (PMID 35693015, 2022). "IDH1/IDH2 mutation was observed in 90% (26/29) of primary LGGs, 38% (6/16) of primary anaplastic gliomas and none (0/8) of the primary GBM." (PMID 23840696, 2013).